CSTB (cystatin B)
Diseases named in the same sentence as CSTB in open-access papers (continued):
Sharing a sentence is not in itself a finding about the gene and the disease.
ovarian tumors (2 papers, 2014 to 2017). "CMPK, as well as cystatin B and β-2-microglobulin, is overexpressed in human epithelial-type ovarian tumors." (PMID 28560285, 2017). "By immunohistochemistry staining, the overexpression of CSTB was observed in human ovarian tumors, including benign, borderline and malignant tumors, albeit at different levels, compared with the normal ovarian tissues that showed negative staining." (PMID 24452274, 2014). "The positive staining (brown color) was mainly distributed in the cytoplasm of the epithelial cells of ovarian tumor and the expression of CSTB protein was weak in benign tumors, moderate in borderline tumors, and strong in malignant tumors." (PMID 24452274, 2014). "By comparison of ovarian tumors with the normal ovarian tissue, we found that the positive rate of CSTB expression was different." (PMID 24452274, 2014). "Overall, these studies indicate that CSTB may be useful as an ovarian tumor marker and a target protein for diagnosis, prognosis and therapy in cancer." (PMID 24452274, 2014). "By comparison of CSTB protein expression associated with age, we found that CSTB expression was not significantly different between younger (≤45 years) and older (>45 years) patients with ovarian tumor (P>0.05)." (PMID 24452274, 2014). "Therefore, the follow-up of patients with an ovarian tumor and the measurement of the serum and urine levels of CSTB in patients may be of great interest and should be proposed as the next investigation." (PMID 24452274, 2014). "However, whether the expression of CSTB in ovarian tumor is regulated by the TGF-β signaling pathway remains unclear." (PMID 24452274, 2014).
Parkinson disease (2 papers, 2020 to 2021). A progressive degenerative disorder of the central nervous system characterized by loss of dopamine producing neurons in the substantia nigra and the presence of Lewy bodies in the substantia nigra and locus coeruleus. "Similarly, decreased expression of CSTB is correlated with disease where mRNA abundance in the peripheral blood has been shown to be decreased in patients with Parkinson’s disease." (PMID 34379632, 2021).
progressive ataxia (2 papers, 2023 to 2025). "The cystatin B-deficient mouse model, Cstb−/−, has been described to present with myoclonic seizures and progressive ataxia." (PMID 38179183, 2023).
tonic-clonic seizures (2 papers, 2009 to 2021). "CSTB knock-out mice also demonstrate increased susceptibility in vivo to severe seizure, including generalized tonic-clonic seizures, and in vitro exhibit neuronal hyperexcitability characterized by decreased seizure threshold." (PMID 19656408, 2009).
trisomy 21 (2 papers, 2023 to 2025). A chromosomal disorder consisting of the presence of an extra chromosome 21. "Thus, it contains 3 copies of the CSTB/Cstb gene and can be used to understand the effect of this on trisomy 21 biology." (PMID 39841661, 2025). "To determine if trisomy 21 results in an increase in CSTB protein in the brains of people who have AD-DS, we compared the abundance of the protein between these individuals and individuals from the general population with EOAD or who were ageing healthily, by western blot." (PMID 37580797, 2023).
ZIKV infection (2 papers, 2022). "Cystatin B (CSTB), the receptor for advanced glycation end products (RAGE), and tyrosine-protein kinase receptor UFO (AXL) have been implicated in ZIKV infection and inflammation." (PMID 36429055, 2022). "In our studies, we also observed decreased CSTB and ZIKV infection in Hofbauer cells, suggesting a possible mechanism of ZIKV restriction in the placenta." (PMID 36429055, 2022). "However, ZIKV infection and CSTB expression were concentrated in the trophoblast villi." (PMID 36429055, 2022). "ZIKV infection significantly upregulated genes related to lysosomal biosynthesis, including LAMP1 and CLCN7 (lysosomal transmembrane proteins); CSTB and CSTD (lysosomal hydrolases); and ATP6V1C1 and ATP6V0D1 (v-ATPase proteins)." (PMID 36405969, 2022). "Our quantitative proteomics results further validate the involvement of the proteins CSTB and AXL in ZIKV infection of the placenta." (PMID 36429055, 2022).
abdominal aortic aneurysm (1 paper, 2021). Enlargement and ballooning of the vessel that supplies arterial blood to the abdomen, pelvis and legs. "Inflammation also plays a key role in abdominal aortic aneurysms, where myeloperoxidase, tissue-type plasminogen activators, and cystatin-B levels were significantly associated with AbAA growth, even after adjusting for baseline AbAA diameter." (PMID 34441429, 2021).
autoimmune disease (1 paper, 2025). A disorder resulting from loss of function or tissue destruction of an organ or multiple organs, arising from humoral or cellular immune responses of the individual to their own tissue constituents. "Notably, CSTB has emerged as a differential biomarker, distinguishing between these two autoimmune diseases." (PMID 39901093, 2025). "Thus, our results revealed that two of the common proteins for T1DM and MS, CSTB and RASFF2, are potential biomarkers for differentiating between these autoimmune diseases." (PMID 39901093, 2025).
bladder tumors (1 paper, 2022). "Both NMP22 and CSTB are tumor markers related to the occurrence and development of bladder tumors." (PMID 35647202, 2022).
brain tumor (1 paper, 2022). "This case-control study aimed to evaluate the expression of cystatin B (CSTB) and deleted in malignant brain tumor 1 (DMBT1) in the saliva of GC patients with healthy individuals to construct diagnostic algorithms using statistical analysis and machine learning methods." (PMID 35488257, 2022).
cholangiocarcinoma (1 paper, 2025). A carcinoma that arises from the intrahepatic biliary tree (intrahepatic cholangiocarcinoma) or from the junction, or adjacent to the junction, of the right and left hepatic ducts (hilar cholangiocarcinoma). "Following the knockdown of CSTB, there was an increase in the apoptosis of intrahepatic cholangiocarcinoma cells." (PMID 39996856, 2025). "Conversely, the overexpression of CSTB was observed to result in a reduction in the apoptosis of intrahepatic cholangiocarcinoma cells." (PMID 39996856, 2025).
dental caries (1 paper, 2025). The decay of a tooth, in which it becomes softened, discolored, and/or porous. "In relation to dental caries, it was shown that cystatin B was increased by more than 13 times in the AEP after exposure to lactic acid, suggesting protection conferred by the acquired pellicle against acids from cariogenic challenges." (PMID 40332163, 2025).
developmental delay (1 paper, 2020). "The first two patients with a homozygous R68X mutation in the CSTB gene present severe phenotypes with microcephaly and developmental delay starting from 3 months of age in one case." (PMID 32378798, 2020).
diabetic nephropathy (1 paper, 2020). "Other potential biomarkers for diabetic nephropathy include miR-21-5p, miR-15b, miR-34a, miR-636, MASP2, CALB1, myeloblastin, elafin, cystatin B, and neutrophil gelatinase-associated lipocalin, all of which increase in the presence of the condition." (PMID 32849923, 2020).
dry eye (1 paper, 2024). "A study comparing the tear fluid from pSS patients with that of non-SS dry eye subjects revealed upregulated protein metabolism involving MMP8, SERPINB5, RPLP2, CSTB, and CST3 in pSS patients compared to controls." (PMID 39408709, 2024).
epileptic seizures (1 paper, 2011). "Presence of 3 copies of the CSTB gene is probably not involved in susceptibility to epileptic seizure in the DS population." (PMID 22140471, 2011).
epithelial ovarian malignant tumor (1 paper, 2014). "Here we demonstrated that CSTB protein was indeed not only overexpressed in epithelial ovarian malignant tumor, but also expressed in benign and borderline tumors; the latter was not reported previously." (PMID 24452274, 2014).
fungal infections (1 paper, 2022). "It should be noted that Cystatin-B is involved in immune responses to bacterial and fungal infections and anti-apoptotic processes in the brain." (PMID 35719393, 2022).
gestational hypertension (1 paper, 2024). "Robust associations (ie, directional consistency across all sensitivity analyses) were observed for 4 of 8 proteins associated with gestational hypertension (CD40, ECP, Gal-3, and NT-proBNP), and 2 of 4 proteins associated with preeclampsia (CSTB and HSP27)." (PMID 38170504, 2024). "Four proteins were associated with preeclampsia: cystatin B (CSTB), ECP, heat shock protein 27 (HSP27), and ST2." (PMID 38170504, 2024). "All robustly associated proteins, except CD40 for gestational hypertension and CSTB for preeclampsia, had directionally consistent associations with the other HDP subtype (eTables 8-9 in Supplement 2)." (PMID 38170504, 2024). "Four were robust to sensitivity analyses for gestational hypertension (cluster of differentiation 40, eosinophil cationic protein [ECP], galectin 3, N-terminal pro–brain natriuretic peptide [NT-proBNP]), and 2 were robust for preeclampsia (cystatin B, heat shock protein 27 [HSP27])." (PMID 38170504, 2024). "Primary analyses identified 10 proteins reflecting pathways with potential roles in the development of HDPs, 6 of which were robust to sensitivity analyses for gestational hypertension (CD40, ECP, Gal-3, NT-proBNP) or preeclampsia (CSTB, HSP27)." (PMID 38170504, 2024).
hematoma (1 paper, 2021). A hematoma is a collection of blood from a vascular structure into an extravascular space. "The other is associated with T cell subcluster 6, which is a hematoma cluster emerging during rebleeding, and is defined by T cell effector genes like CXCR4, TXN, and CSTB (effector module score 2)." (PMID 33749664, 2021).
intrahepatic cholangiocarcinoma (1 paper, 2025). A carcinoma that arises from the intrahepatic bile duct epithelium in any site of the intrahepatic biliary tree. "The expression of CSTB was detected in four intrahepatic cholangiocarcinoma cell lines, including RBE, HCCC9810, CLLP1, and HUCCT-1." (PMID 39996856, 2025). "Nevertheless, the function of CSTB in intrahepatic cholangiocarcinoma (iCCA) is yet to be fully elucidated." (PMID 39996856, 2025). "The objective of this study is to investigate the pivotal function of CSTB in the pathogenesis of intrahepatic cholangiocarcinoma and to identify novel potential therapeutic targets for this disease." (PMID 39996856, 2025).
laryngeal carcinoma (1 paper, 2015). Carcinoma that arises from the laryngeal epithelium. "Additionally, in more than one proteomics study, cystatin-B, heat shock protein beta-1, and isoform 1 of serum albumin were deemed to be related to laryngeal carcinoma, but without in-depth functional research or clinical validation." (PMID 25874882, 2015).
laryngeal squamous cell carcinoma (1 paper, 2021). A squamous cell carcinoma that arises from the larynx. "CSTB was downregulated in HNSCC, which was consistent with the findings of our study and a previous study on HNSCC (i.e., laryngeal squamous cell carcinoma)." (PMID 34504787, 2021).
lung disease (1 paper, 2024). "The cysteine protease inhibitors cystatin B, cystatin SA and lipocalin-1 are decreased in frequent exacerbators, but their specific role in lung disease has not been characterised." (PMID 38135443, 2024).
melanoma (1 paper, 2023). A malignant, usually aggressive tumor composed of atypical, neoplastic melanocytes. "The results revealed that the CSTB, GBF1, TYR, RAC1, SLC2A1 and NOTCH3-coding proteins were significantly enriched in melanoma samples, while CEBPB-coding protein had low expression in melanoma samples." (PMID 37217516, 2023). "However, the roles of CSTB, GBF1, PML and ICAM1 in melanoma development were still unclear, which deserved to further exploration." (PMID 37217516, 2023).
multiple sclerosis (1 paper, 2014). A progressive autoimmune disorder affecting the central nervous system resulting in demyelination. "Moreover, microglia-derived cathepsin B, a target protein of CSTB, has been shown to have a role in WM damage in a mouse model of multiple sclerosis." (PMID 24603771, 2014).
neuroblastoma (1 paper, 2011). Neuroblastoma (NB) is the most common solid, extracranial childhood tumor. "The finding that both over expression of wild-type or EPM1 mutants of cystatin B in neuroblastoma cells generates cytoplasmic aggregates has suggested that cystatin B in vivo has a polymeric structure sensitive to the redox environment." (PMID 22140471, 2011).
neuropathic pain (1 paper, 2016). Chronic pain caused by damage to nerve fibers. "Of the 47 investigated proteins, 21 (cathepsin S, CCL2, CCL4, CCL16, CFIII, CXCL5, cystatin B, E-Selectin, Fas/TNFRSF6, follistatin, GDF-15, GH, ICAM1, IL8, KLK5, MMP2, MMP9, P-Selectin, sortilin, TIMP4 and VEGF) were detectable by multiplex SP-PLA in ≥ 95% of the neuropathic pain patient samples." (PMID 26914813, 2016).
Oral Squamous Cell Carcinoma (1 paper, 2021). "Our study found that CSTB was downregulated in both oral squamous cell carcinoma (OSCC) tissues and cells compared with normal controls." (PMID 34504787, 2021).
osteoarthritis (1 paper, 2021). A noninflammatory degenerative joint disease occurring chiefly in older persons, characterized by degeneration of the articular cartilage, hypertrophy of bone at the margins and changes in the synovial membrane. "Furthermore, inflammation modulators (such as CSTB, CTSD, and CTSZ), which have been reported to contribute to osteoarthritis, were more highly expressed in the medial than lateral meniscus." (PMID 34360947, 2021).
ovarian serous malignant tumor (1 paper, 2014). "Although the detection of CSTB in ovarian serous malignant tumor has been reported, this is the first report showing that CSTB was also expressed in mucinous and clear cell tumors." (PMID 24452274, 2014).
pancreatic ductal adenocarcinoma (1 paper, 2025). An infiltrating adenocarcinoma that arises from the epithelial cells of the pancreas. "In pancreatic ductal adenocarcinoma, CSTB competes with cystatin C (CSTC) to bind cathepsin B (CTSB), but CSTC has stronger cathepsin inhibitory activity." (PMID 39996856, 2025). "The high expression of CSTB in pancreatic ductal adenocarcinoma reduces the inhibition of CTSB, thereby acting as a tumor-promoting factor." (PMID 39996856, 2025).
parasitic infections (1 paper, 2025). "Future studies should explore the upstream regulatory network of CSTB, its interaction with other immune signaling molecules, and its roles in different types of immune challenges such as viral or parasitic infections." (PMID 41017465, 2025).
periodontitis (1 paper, 2011). An acute or chronic inflammatory process that affects the tissues that surround and support the teeth. "The expression of cystatin-B was decreased in periodontitis patients compared to healthy controls." (PMID 21794177, 2011).
psoriasis (1 paper, 2021). An autoimmune condition characterized by red, well-delineated plaques with silvery scales that are usually on the extensor surfaces and scalp. "Moreover, in psoriasis, a condition that manifests as uncontrolled keratinocyte proliferation and epithelial hyperplasia, the amount of CSTB is increased, which is usually not seen in healthy epidermis (i.e., normal skin)." (PMID 34504787, 2021).
rectal cancer (1 paper, 2023). A primary or metastatic malignant neoplasm that affects the rectum. "The bulk expression of CSTB and TM4SF1 was associated with both advanced tumor stage and poor PFS time in both colon and rectal cancer patients." (PMID 36816947, 2023).
salivary gland tumors (1 paper, 2024). "Some of the identified peptides were derived from proteins previously suggested as potential biomarkers of salivary gland tumors (ANXA1, BPIFA2, FGB, GAPDH, HSPB1, IGHG1, VIM) or tumors of other tissues or organs (SERPINA1, APOA2, CSTB, GSTP1, S100A8, S100A9, TPI1)." (PMID 39201484, 2024).
sarcopenia (1 paper, 2022). Progressive decline in muscle mass due to aging which results in decreased functional capacity of muscles. "The top three identified hub genes are UPF3A, CSTB and PEA15, which were all affiliated to common genes of sarcopenia and proliferating myoblasts of T2DM." (PMID 35271662, 2022).
serous ovarian carcinomas (1 paper, 2014). "It has been reported that CSTB, derived from serous ovarian carcinomas, strongly inhibits papain and cathepsin L and moderately inhibits cathepsin B." (PMID 24452274, 2014).
squamous cell lung carcinoma (1 paper, 2025). A carcinoma arising from squamous bronchial epithelial cells. "No causal relationships were found for genetically predicted Cystatin B (ebi‐a‐GCST90085722), Cystatin B (prot‐b‐3), Cystatin D, Cystatin F, Cystatin M (prot‐a‐703), or Cystatin M (prot‐a‐704) with squamous cell lung carcinoma (all p > 0.05)." (PMID 40641363, 2025).
Stroke (1 paper, 2020). Sudden impairment of blood flow to a part of the brain due to occlusion or rupture of an artery to the brain. "The chemo-attractant protein IL-16 and cathepsin enzyme inhibitor CSTB were the only proteins found elevated in patients with improved stroke volume." (PMID 33122738, 2020).
Tremor (1 paper, 2025). An unintentional, oscillating to-and-fro muscle movement about a joint axis. "Progressive tremor was associated with genes CACNA1A, CSTB, and SAMD9L." (PMID 40326640, 2025).